PRDM14 (PR/SET domain 14)
Diseases named in the same sentence as PRDM14 in open-access papers (continued):
Sharing a sentence is not in itself a finding about the gene and the disease.
pancreatitis (1 paper, 2018). Inflammation of the pancreas. "Using pancreatitis mouse models, we observed that cerulein‐induced chronic inflammation on successive days increases PRDM14 expression in the pancreas of normal mice." (PMID 30338223, 2018). "To assess the relation between inflammation and PRDM14 expression, we used a mouse model of pancreatitis, which was induced upon intraperitoneal injection of cerulein." (PMID 30338223, 2018).
tubular adenoma (1 paper, 2016). A usually polypoid neoplasm arising from the glandular epithelium. "The PRDM14 (NM_024504) gene displayed methylation in 28 CpG sites in this gene's promoter region within tumor samples, while none of them was found to be methylated in normal, tubular adenoma, and tubulovillous adenoma samples." (PMID 27688749, 2016).
cancer (31 papers, 2008 to 2025). A tumor composed of atypical neoplastic, often pleomorphic cells that invade other tissues. "Since the first observation, PRDM14 has been implicated in many other cancer types, most of them showing a similar mechanism involving its role in stem cell pluripotency." (PMID 32290321, 2020). "Of note, through direct regulation of Notch pathway, PRDM14 was certainly associated with cancer stem cells and thus chemoresistance." (PMID 32290321, 2020). "These high-risk features of PRDM14-expressing cancers reinforce the significance of determining its molecular function in tumorigenesis." (PMID 24046360, 2013). "PRDM14, a potency gene implicated in a wide variety of cancers, has been proposed to be a driver of CICs." (PMID 24046360, 2013). "Together, our data suggest that PRDM14 expands a progenitor cell population while promoting a permissive epigenetic state for the creation of driver mutations (here, in Notch1), enabling cancer development through the misappropriation of endogenous cellular DNA recombination machinery." (PMID 27106930, 2016). "PRDM14 was also shown to be highly expressed in numerous cancers, but its precise roles in tumor formation and metastasis are unclear." (PMID 38710919, 2024). "Some epigenetic changes, such as reduction of the DNA methylation of the proto-oncogene and stemness gene promoters, as well as enhanced methylation of tumour suppressor genes in cancer cells, were mediated by PRDM14." (PMID 34884658, 2021). "In cancer cells, PRDM14 conferred stem cell-like phenotypes by regulation of the expression of genes involved in cancer stemness, metastasis, and chemoresistance in vitro." (PMID 34884658, 2021). "In vitro experiments showed that while ectopic PRDM14 expression enhanced cancer cell growth and resistance to chemotherapeutic drugs, PRDM14 knockdown was able to induce apoptosis and increase sensitivity to chemotherapeutic drugs." (PMID 32290321, 2020). "PRDM14 is a transcription factor that maintains pluripotency in embryonic stem cells and is overexpressed in several cancers." (PMID 30338223, 2018). "Among the four groups of sorted OECM1 cells, PRDM14 is exclusively expressed by GRP78HiPGN− cells, indicating a strong influence of cell surface GRP78 on the up-regulation of PRDM14 for cancer stemness." (PMID 29323121, 2018). "Our results suggest that inflammation increases the expression of PRDM14, which regulates cancer stem‐like phenotypes, and this occurs prior to PDAC initiation and progression." (PMID 30338223, 2018). "PRDM14 regulated the expression of genes and miRNAs involved in cancer cell stemness, metastasis, and drug resistance." (PMID 28423353, 2017). "Here, we examined the phenotypic characteristics and epigenetic and gene expression profiles of cancer cells that differentially express PRDM14, and assessed the potential of PRDM14-targeted cancer therapy." (PMID 28423353, 2017). "Our results indicate that PRDM14 expression is higher in tumorspheres than in monolayers of cancer cells." (PMID 28423353, 2017). "Although PRDM14 is elevated in several cancers, it is unclear if and how PRDM14 confers stem cell-like properties and epigenetic changes to cancer cells." (PMID 28423353, 2017). "Due to the 3′-UTR sequence length decrease in many siRNA-resistant cancers, we used sequences specific to the coding region of PRDM14 (#2 and #3)." (PMID 28423353, 2017). "PRDM14 reduced the DNA methylation of proto-oncogene and stemness gene promoters but enhanced methylation of tumor suppressor genes in cancer cells." (PMID 28423353, 2017). "PRDM14 conferred stem cell-like phenotypes to cancer cells and regulated the expression of genes involved in cancer stemness, metastasis, and chemoresistance." (PMID 28423353, 2017). "This analysis showed increasing DNA methylation from normal to cancer with an average rate range from 0.09 (L3MBTL1) to 0.27 (PRDM14)." (PMID 27688749, 2016).
cancer (continued). "Our ultimate goal was to understand how PRDM14 initiates cancer and to exploit this knowledge for cancer treatment." (PMID 27106930, 2016). "As a potential multi-cancer oncogene, a single mouse model that allows for inducible expression of Prdm14 in specific cell types is desirable." (PMID 24046360, 2013). "The R26PR mouse line described here is a powerful model for the spatial and temporal control of Prdm14 misexpression, which can be used to investigate the role of PRDM14 in multiple cancer types." (PMID 24046360, 2013). "Future studies will elucidate the molecular changes that occur following Prdm14 overexpression and shed light on how these changes contribute to cancer development and progression." (PMID 24046360, 2013). "Little is known about the role of PRDM14 in cancer initiation and maintenance in humans, but its aberrant expression and role in chemoresistance in cancers has been noted." (PMID 23487523, 2012). "Aberrant Prdm14 expression in somatic cells not only initiates cancer but also induces profound DNA rearrangements." (PMID 23487523, 2012). "Further work on Prdm14 will provide a greater knowledge of the role of SET domain genes in cancer development, as well as a direct link between tumorigenesis and ES cell biology." (PMID 19043588, 2008). "Whether its regulation by PRDM14, which normally occurs in ESCs, is hijacked in cancer cells requires further analysis." (PMID 38710919, 2024). "In particular, the PRDM14 protein was present in 38% of BC patients’ biopsies, and its expression was associated with a poor prognosis for BC patients regardless of cancer stage." (PMID 34884658, 2021). "Thus, inhibition of PRDM14 has also been suggested as a potential target of treatment in cancer therapy." (PMID 33287742, 2020). "It has been proposed that PRDM14 (corresponding gene) expression could influence G1/S transition thus enabling cell proliferation and facilitate cancer stem cell like properties and chemoresistance." (PMID 33287742, 2020). "In order to elucidate this dual role of PRDM14 in cancer further studies are still required." (PMID 32290321, 2020). "More recently, in vitro and in vivo experiments were set up to ascertain whether and how PRDM14 could also confer stem cell-like properties and epigenetic changes to cancer cells." (PMID 32290321, 2020). "We previously reported that PRDM14 is overexpressed and regulates cancer stem‐like phenotypes in PDAC, and herein, we assess whether PRDM14 expression increases prior to tumorigenesis." (PMID 30338223, 2018). "Our findings suggest that PRDM14 inhibition may be an effective and novel therapy for cancer stem cells." (PMID 28423353, 2017). "Because polycomb proteins and DNA methyltransferases are aberrantly overexpressed in cancer cells, PRDM14 might induce DNA methylation in genome areas with bivalent chromatin to readily induce epigenetic changes." (PMID 28423353, 2017). "Since PRDM14 overexpression occurs during the early stages of cancer, PRDM14 may serve as an initial trigger of epigenetic changes in tumors." (PMID 28423353, 2017). "Thus, PRDM14 is involved in maintenance of the CSC phenotype and inhibition of PRDM14 expression induces cancer cell differentiation." (PMID 28423353, 2017). "Genes that are overexpressed in cancers, such as PRDM14, may be effective targets for new therapies." (PMID 28423353, 2017). "PRDM14’s role in cancer initiation may well be related to its role in inducing and maintaining a pluripotent state." (PMID 23487523, 2012). "Unfortunately, the transcriptional targets of Prdm14 remain to be determined; finding these may further elucidate the direct role of Prdm14 in cancer development." (PMID 19043588, 2008). "There is substantial evidence that PRDM14 is involved in human cancer as well." (PMID 19043588, 2008). "Therefore, we tested this delivery method for PRDM14 chimera RNAi for cancer treatment." (PMID 28423353, 2017).
cancer (continued). "Researchers analyzed the expression of three miRNAs (miR-21, miR-31, and miR-210) and the methylation of three genes (RASSF1A, PRDM14, and 3OST2) in sputum samples from NSCLC patients and cancer-free smokers." (PMID 40332376, 2025). "In fact, many germ cell markers were used to identify cancer stem cells, such as SSEA1, CD117, Sox2, PRDM14." (PMID 36435765, 2022). "A potential role for PRDM10 in cancer is to be highly expected since several better studied members of the PRDM family, PRDM2, PRDM3, PRDM5, and PRDM14, are known to play an important role in a variety of cancers." (PMID 31143550, 2019). "The results considering the three-gene signature (POU5F1P1, PRDM14, and FAM84B) analyzed in 10 different cancer studies consisting 4,641 samples were limited to more than a 20% alteration frequency and minimum of 100 samples in the dataset." (PMID 30287838, 2018). "Recently, we reported that PRDM14 is overexpressed in PDAC tissues, compared to normal pancreatic tissues, and silencing the expression decreased cancer stem‐like phenotypes including side population (SP) cells, tumor formation, and liver metastasis." (PMID 30338223, 2018). "Therefore, we hypothesized that expression of Prdm14 in somatic cells causes cancer by activating self-renewal without appropriate prevention of or response to DNA damage." (PMID 23487523, 2012). "Later, PRDM14 silencing was found through hypermethylation of its promoter in HPV-positive cancers, and ectopic expression of PRDM14 in HPV16-positive cancer cell lines induced apoptosis, possibly due to a direct upregulation of the pro-apoptotic genes NOXA and PUMA." (PMID 32290321, 2020). "Although this different role of PRDM14 could be explained with the expression of HPV oncogenic proteins in those tumors, the same epigenetic changes were found also in other cancer types." (PMID 32290321, 2020). "In-vivo tumorigenic potential and sphere-forming ability was greatly facilitated in PRDM14-overexpressing cancer cells, although these findings did not fully support the role of PRMD14 in cancer stemness." (PMID 31013960, 2019). "The PRDI-BF1 and RIZ (PR) domain zinc finger protein 14 (PRDM14), known as a transcription factor that maintains pluripotency in stem cells via epigenetic regulations, reduced the methylation of proto-oncogene and stemness gene promoters in cancer cells." (PMID 31013960, 2019). "PRDM14 is overexpressed in PDAC and regulates cancer stem‐like phenotypes." (PMID 30338223, 2018). "In addition to the described genes, we can individually identify WHSC1, PRDM14 and ANXA11 genes which are involved in autoimmune disorders and in some cancers." (PMID 30075788, 2018). "Treatment with anti-PRDM14 therapy by siRNA/CaP hybrid micelles, however, should not affect the expression of PRDM14 mRNA in normal ovarian tissue since this technique specifically accumulates siRNA in targeted cancer tissues by EPR effects." (PMID 28423353, 2017). "PRDM14 expression did not promote cancer cell proliferation in 2D culture but enhanced tumor cell proliferation in vivo or in a near-in vivo environment, such as low attachment growth conditions." (PMID 28423353, 2017). "Here, we examined whether PRDM14 induces CSC-like phenotypes and influences the epigenetic state of cancer cells." (PMID 28423353, 2017). "The present study examined PRDM14 expression in cancer tissues and its effect on CSC formation by investigating whether PRDM14 induces biological properties consistent with the CSC phenotype and influences the epigenetic state of cancer cells." (PMID 28423353, 2017). "In our expression experiments, PRDM14 mRNA was found in normal ovarian tissue derived from non-cancerous parts of cancer tissues." (PMID 28423353, 2017). "Given the high PRDM14 expression in tumors and its ability to mediate pluripotency in ES cells, we hypothesized that PRDM14 contributes to CSC formation and aberrant epigenetic status in cancer." (PMID 28423353, 2017).
cancer (continued). "We analyze expression of 3 miRNAs (miR-21, miR-31, and miR-210) and methylation of 3 genes (RASSF1A, PRDM14, and 3OST2), which were previously identified as potential biomarkers for NSCLC, in sputum of a set of 117 stage I NSCLC patients and 174 cancer-free smokers." (PMID 27777637, 2016). "Although inflammation increased PRDM14 expression in PDAC cells without enhancing cancer stem‐like phenotypes, inflammation may contribute to maintain the overexpression and tumor phenotypes in the cancer." (PMID 30338223, 2018). "Additionally, however, PRDM14 induced DNA methylation to repress several tumor suppressor genes in cancer cells, but not ES cells." (PMID 28423353, 2017). "Therefore, PRDM14, like tenascin C, may be required for CSC plasticity and the formation of tumorsphere initiating cells, leading to more aggressive cancer phenotypes." (PMID 28423353, 2017). "Because PRDM14 is not expressed beyond embryogenesis, it could represent an ideal druggable target in new anti-cancer therapies." (PMID 24046360, 2013). "Therefore, we investigated whether PRDM14 also inhibits DNA methylation in tumorigenic and non-tumorigenic breast cells to promote cancer growth." (PMID 28423353, 2017). "Importantly, our work shows that PRDM14 may be an ideal target in many tumor types for eliminating residual cancer cells without adverse effects." (PMID 28423353, 2017). "Here we identified specific CpG sites in L3MBTL1, NKX6-2, PREX1, TRAF7, PRDM14,and NEFM as primarily methylated in cancer specimens but not in other colonic lesions; these genes were also found to be implicated in many important pathways relevant to neoplastic transformation." (PMID 27688749, 2016).
tumor (24 papers, 2008 to 2024). "In addition, silencing of PRDM14 expression reduced tumour size and metastasis in vivo, while conditional loss of PRDM14 function improved survival of MMTV-Wnt-1 transgenic mice, a spontaneous model of murine BC." (PMID 34884658, 2021). "The abnormal methylation of PRDM14 can change the chromatin structure, DNA conformation and the interaction mode of DNA and protein, it can suppress transcription and expression of the gene, which caused the occurrence, development and metastasis of tumor." (PMID 26903163, 2016). "PRDM14′s role as a tumor suppressor—and whether its variant isoform exists—remains unknown." (PMID 36982660, 2023). "PRDM14 expression may also be associated with anti‐inflammatory effects on tumor phenotypes." (PMID 30338223, 2018). "Interestingly, expression of the pluripotency marker Oct-3/4 was observed in all AKXD tumors examined here, allowing for the possibility that pluripotency may play a role in tumor susceptibility when Prdm14 is overexpressed." (PMID 19043588, 2008). "Potentially, it would be interesting to study PRDM14 in MCL tissue to understand if it is expressed by the tumor cells or secreted by the immune system." (PMID 33287742, 2020). "The analysis of the gene expression profile indicated that PRDM14 overexpressing cells showed significant enrichment of pluripotent genes and enhancement of the tumor-initiating pathway (WNT and RAS signaling)." (PMID 33291744, 2020). "PRDM14-specific chimera RNAi alone decreased orthotopically grafted tumor size, which further decreased when the mice were additionally treated with DOC." (PMID 28423353, 2017). "PRDM14-specific siRNA alone decreased tumor size, an effect that was enhanced with the addition of anticancer drugs." (PMID 28423353, 2017). "To ensure that the anti-tumor effects of PRDM14-siRNA treatment were due to PRDM14 inhibition, we generated Prdm14 KO; Wnt-1 transgenic mice." (PMID 28423353, 2017). "Inhibition of PRDM14 expression in the tumor by chimera RNAi was confirmed using qRT-PCR and immunohistochemical analyses." (PMID 28423353, 2017). "The retroviral insertion in tumor 27-186 is located approximately 450 bp from the first exon of Prdm14 between the 27-001 and 27-142 insertions and integrated in the same orientation as Prdm14." (PMID 19043588, 2008). "Indeed, possible behavior as a tumor suppressor gene has emerged from several studies reporting alterations in the PRDM14 promoter methylation." (PMID 32290321, 2020). "Overall, the oncogenic functions of PRDM14 described so far involve its full-length isoform containing the PR domain; however, it is unknown whether a PR− isoform exists for PRDM14, or whether it has tumor suppressor activity." (PMID 32290321, 2020). "While some such as PRDM2 and PRDM5 act as tumor suppressors, PRDM14 appears to be an oncogene." (PMID 31143550, 2019). "Administration of PRDM14 siRNA using CaP hybrid micelles reduced tumor size and metastases in vivo." (PMID 28423353, 2017). "Using calcium phosphate hybrid micelles as an RNAi delivery system, silencing of PRDM14 expression by chimera RNAi reduced tumor size and metastasis in vivo without causing adverse effects." (PMID 28423353, 2017). "We examined the effect of PRDM14-siRNA administration on tumor growth in vivo." (PMID 28423353, 2017). "Tumor growth in vitro was suppressed by a PRDM14 siRNA but was unaffected by an shRNA construct." (PMID 28423353, 2017). "We suggest that the activity of PRDM14 is largely context-specific, so a unique set of PRDM14 binding partners and activities may be present in pre-leukemic and tumor cells, and may include HMTases." (PMID 27106930, 2016). "Together, these observations suggest that the function of Prdm14 in tumor development may be promoted in cells with a less differentiated phenotype." (PMID 19043588, 2008). "Furthermore, in one Evi32 tumor, expression of Prdm14 is driven from the LTR elements of the integrated provirus." (PMID 19043588, 2008).